HOXD8 (homeobox D8)
Description:
Sequence-specific transcription factor which is part of a developmental regulatory system that provides cells with specific positional identities on the anterior-posterior axis.
Synonyms: HOX4E; HOX4; HOX5.4
Tractability: No criterion of Open Targets' tractability assessment is met for any kind of drug.
Gene: Protein-coding gene on chromosome 2 (176,129,694 to 176,132,695, forward strand). Ensembl gene ENSG00000175879.
Subcellular location: Nucleus
Gene Ontology:
Molecular function: DNA-binding transcription activator activity, RNA polymerase II-specific; protein binding; RNA polymerase II transcription regulatory region sequence-specific DNA binding; sequence-specific double-stranded DNA binding; DNA-binding transcription factor activity, RNA polymerase II-specific; DNA binding; DNA-binding transcription factor activity
Biological process: positive regulation of transcription by RNA polymerase II; anterior/posterior axis specification, embryo; regulation of transcription by RNA polymerase II; regulation of DNA-templated transcription
Cellular component: chromatin; nucleus
Genetic constraint (gnomAD): Loss-of-function variants: 16 observed, 21.08 expected, observed/expected ratio (o/e) 0.76, 90% interval 0.51 to 1.15. The synonymous counts are far from expectation, so gnomAD's model fits this gene poorly and the ratio says little. Missense variants: 498 observed, 353.73 expected, observed/expected ratio (o/e) 1.41, 90% interval 1.31 to 1.52. Synonymous variants: 197 observed, 148.98 expected, observed/expected ratio (o/e) 1.32, 90% interval 1.18 to 1.49.
Homologues: Orthologues: chimpanzee HOXD8 (98% identical), macaque HOXD8 (98% identical), pig HOXD8 (96% identical), mouse Hoxd8 (89% identical), rat Hoxd8 (84% identical), guinea pig HOXD8 (75% identical), tropical clawed frog hoxd8 (55% identical). Paralogues in human: HOXC8 (52% identical), HOXB8 (51% identical), HOXA7 (28% identical), HOXB5 (28% identical), HOXB6 (28% identical), HOXB7 (27% identical), HOXA6 (26% identical), HOXA5 (26% identical), HOXD4 (25% identical), HOXA4 (25% identical), HOXC6 (25% identical), HOXB4 (23% identical), and 30 more.